PCNA (proliferating cell nuclear antigen)
Diseases named in the same sentence as PCNA in open-access papers (continued):
Sharing a sentence is not in itself a finding about the gene and the disease.
melanoma (51 papers, 2007 to 2025). A malignant, usually aggressive tumor composed of atypical, neoplastic melanocytes. "Like sorafenib, oral administration of fisetin monotherapy significantly inhibited the tumor growth of BRAF-mutated melanoma cells in nude mice by inhibiting tumor cell proliferation markers (PCNA, Ki67 and cyclin D1)." (PMID 26299806, 2015). "There were significantly higher staining of proliferation markers Ki-67 and PCNA in HMGB1-proficient melanoma tumors than HMGB1-deficient tumors." (PMID 25051367, 2014). "Oral administration of curcumin has been reported to cause down regulation of anti-apoptotic Bcl-2 and proliferating cell nuclear antigen (PCNA) in subcutaneous melanoma tumors, possibly regulated by microRNA." (PMID 25102117, 2014). "These regulators include MAPK signaling pathway indicators p-BRAF and p-ERK, metastatic markers N-Cadherin and Vimentin, proliferative marker PCNA, and melanoma-specific transcription factor SOX10." (PMID 41284701, 2025). "In vivo experiments also confirmed that overexpression of MLLT3 significantly reduced the growth of melanoma, the metastasis rate, and the expression of PCNA and CD133." (PMID 39716999, 2025). "The expression of PCNA in both the melanoma line and the A549 line of microcell subpopulations shows that DNA repair-related processes occurred." (PMID 39062149, 2024). "After 48 h, melanoma cell proliferation was analyzed by quantitating the levels of PCNA and through BrdU incorporation." (PMID 33924099, 2021). "Human trials have shown that PCNA can be predictive of survival in patients with malignant melanoma." (PMID 34200642, 2021). "Along the same line, increased expression of TXNIP in On-treatment specimens was associated with decreased expression of the proliferation marker PCNA and lower proportion of Ki67-positive melanoma cells in 10 out of the 12 patient samples analyzed." (PMID 33846376, 2021). "On the other hand, TNFR1 KO tumors displayed reduced PCNA expression, suggestive of a decrease in cell proliferation of melanoma cells." (PMID 33202705, 2020). "Similar to human melanoma, equine melanomas are typically positive for S100, PCNA, HMB‐45, Ki‐67, T‐311, and CD44 by immunohistochemistry." (PMID 32652526, 2020). "Immunohistochemical staining was performed to detect the expression of iNOS and hTERT, p-p65, Epcam, CD44, PCNA in mice with melanoma xenografts." (PMID 30717768, 2019). "Regarding proliferation, PCNA expression levels and MI are significantly elevated in melanoma compared to benign biopsies." (PMID 28460440, 2017). "On the other hand, we analyzed the anti-proliferative effect of chaetocin on the melanoma tumor xenografts using immunohistochemical staining for the detection of PCNA expression." (PMID 28419143, 2017). "To gain insights into the positive role of SHP2 in melanoma cell viability, we examined the proliferation marker PCNA and apoptosis marker cleaved PARP after SHP2 overexpression or knockdown in MeWo cells." (PMID 27650545, 2016). "In our recent study, we showed that lupeol suppressed tumor growth in melanoma-bearing mice by attenuating proliferating cell nuclear factor (PCNA) and Ki67, which are highly expressed in melanoma or other tumors." (PMID 25392802, 2014). "Determination of the immunofluorescence intensity of the PCNA proliferation marker in the nuclei of melanoma cells demonstrated a significant decrease in the nuclear presence of this protein in the melanoma cells of animals treated with HPL as well as with 3HFWC + HPL." (PMID 36770334, 2023). "In addition to promoting apoptosis and inhibiting proliferating cell nuclear antigen (PCNA) in human melanoma cells, GSPE decreased β-catenin levels in the cytoplasm and nucleus of the Wnt/β-catenin signaling pathway." (PMID 33339407, 2020). "Moreover, in order to confirm the effect of the αM/MPEG-PCL nanomicelles on the melanoma cell proliferation, we performed proliferating cell nuclear antigen (PCNA) stained." (PMID 30770785, 2019).
melanoma (continued). "The limited induction of PCNA may be responsible for the limited GGR response to cisplatin-induced DNA damage in melanoma." (PMID 23940574, 2013). "It is interesting to learn how melanoma cells can still manage to grow vigorously (as indicated by the 12.6-fold increase of PCNA expression level) despite the surveillance of cell cycle progression checkpoints and apoptotic pathways in the context of such drastic alterations in multiple pathways." (PMID 17594473, 2007). "Thus interaction between NKp44 on pDCs and PCNA on tumor cells may explain pDC dysfunction in melanoma." (PMID 36353633, 2022). "The PCNA-positive cells in the αM/MPEG-PCL nanomicelles group were much fewer than the ones in the other groups, suggesting the αM/MPEG-PCL nanomicelles blocked melanoma associated with cell proliferation suppression and possessed better effect compared to the free αM." (PMID 30770785, 2019). "The increase in PCNA+/TYRP1+ cells within the RXRαep−/−|Tyr-NRASQ61K|Cdk4R24C/R24C skin as compared to the RxrαL2/L2 control mice indicated the presence of a large volume of proliferating melanocytes in the mutant melanomas in absence or in presence of acute UVB." (PMID 29121869, 2017). "Significant induction of PCNA in response to cisplatin treatment in melanocytes in this study further confirms the role of PCNA in DNA damage response, but it is not clear if the absence of PCNA induction in the melanoma cell lines is a consequence or cause of the absence of GGR induction." (PMID 23940574, 2013). "As a result, the Notch pathway is activated, leading to the transcription of c-MYC, proliferating cell nuclear antigen (PCNA), and CDK4, which are involved in melanoma progression." (PMID 41463281, 2025). "Compared to those in the control group, expression levels of full-length PARP1 and proliferative marker PCNA were significantly decreased in the LNT group, indicating the anti-proliferative and pro-apoptotic effects of LNT in melanoma." (PMID 39744474, 2025). "The effect of monensin on the protein expression levels of the proliferative marker PCNA of 4T1-Luc2-Luc2 cells was evaluated in comparison with that exerted on murine hepatocarcinoma Hepa-C1C7, murine melanoma B16, and human ovarian cancer SKOV-3 cells." (PMID 39936977, 2025). "Consistent with increased PCNA and TOP2 expression, cyclin D1 protein levels were also markedly enhanced after induction of CD133 expression in both melanoma cell lines." (PMID 38727313, 2024). "In PCNA+ human melanoma, infiltrating pDCs showed increased NKp44 levels, which correlated with a low activation level, suggesting that the interaction of NKp44 with PCNA expressed by melanoma cells could contribute to pDC dysfunctions typically observed in melanoma patients." (PMID 38504978, 2024). "Microscopic analysis of the proliferative capacity of melanoma cells from tumors of animals exposed to HPL and 3HFWC alone or in combination was performed by the mitotic index analysis and PCNA immunopositivity analysis." (PMID 36770334, 2023). "SNAP-Pol δ and Halo-PCNA proteins were co-expressed under the control of doxycycline-inducible promoters from constructs stably integrated into LOX cells, a human melanoma cell line." (PMID 32023453, 2020). "Mosaic vessel and VM channel formation in a B16F10 mouse melanoma model are reduced by thalidomide which inhibits expression of VEGF, NFκB, PCNA, MMP-2 and MMP-9." (PMID 29112161, 2017). "Thalidomide promoted B16F10 melanoma cell necrosis and inhibited VEGF, NF-κB, PCNA, MMP-2 and MMP-9 expression." (PMID 18983651, 2008). "Utilizing RT-qPCR and Wes ProteinSimple analyses, we found modulation in the markers of cell proliferation (PCNA), survival (Survivin) and angiogenesis (VEGF) in response to SIRT3 manipulation, further supporting the pro-proliferative role of SIRT3 in melanoma." (PMID 33937086, 2021).
melanoma (continued). "Strikingly, overexpression of LINC-PINT significantly reduced melanoma cells progression via downregulating the potential target genes CDK1, CCNA2, AURKA, and PCNA through recruiting EZH2 protein, which in turn mediated the trimethylation of H3K27 of promoter regions of target genes." (PMID 31921860, 2019). "A previous PPI network analyses conducted in a whole gene expression dataset of 31 primary melanomas and 52 metastases reported a PPI network in which PCNA, CDK1, MAD2L1, RFC4 and BRCA1 genes showed highest degree centrality values among upregulated genes in metastases." (PMID 28030792, 2017). "The PCNA (proliferating cell nuclear antigen) in pigmented and non-pigmented melanomas was also assessed." (PMID 29056717, 2016). "The GGR regulators, BRCA1 and PCNA, were induced in melanocytes after cisplatin, but not in melanoma cell lines." (PMID 23940574, 2013). "In this study we have confirmed that the GGR regulators, BRCA1 and PCNA, are induced in the normal cellular response to cisplatin induced DNA damage, but there is complete absence of induction of these regulators in melanoma cell lines." (PMID 23940574, 2013). "Our results on the down-regulation of Bcl-2 and PCNA expression were further supported by flow cytometric cell cycle analyses of curcumin-treated B78H1 cells, indicating that curcumin affects both apoptosis and proliferation of this melanoma cell line." (PMID 24349037, 2013). "Consequently, the downregulation of PCNA protein and the CDC25A/CyclinB1/CDK1 pathway may be the mechanism of ZBSO against melanoma." (PMID 37081962, 2023). "In anti-melanomas compounds, we have demonstrated that alternol could decrease the expression levels of cyclin-dependent kinase 2 (CDK2) and proliferating cell nuclear antigen (PCNA), and activate CDK inhibitor1A (p21) to inhibit melanoma B16F0 cell proliferation." (PMID 27796318, 2016). "In support of previous reports, silencing MYO1B, which augmented nuclear PTEN level, induced cell apoptosis of MEFs and melanoma cell B16F10 as reflected by enhanced Annexin-V immunostaining and increased cleaved caspase 3 level without a change in PCNA level." (PMID 31349190, 2019). "PCNA, BRCA1 and XPB displayed a lack of induction and highly correlated with altered expression in melanoma after cisplatin treatment by GSEA, therefore they were further investigated in 157 primary and metastatic melanoma tumours." (PMID 23940574, 2013). "Importantly, DNA repair transcripts PCNA and BRCA1, both of which have previously been reported to regulate DDB1 and DDB2 transcript expression, had significantly higher induction in melanocytes 24 hours after cisplatin treatment but not in the majority of the melanoma cell lines." (PMID 23940574, 2013).
prostate carcinoma (50 papers, 2004 to 2026). A carcinoma that arises from epithelial cells of the prostate gland. "In prostate cancer, we and others have shown that PCNA overexpression is associated with advanced Gleason scores and pathological stages, and has significant prognostic value for disease-free survival." (PMID 40391771, 2025). "Proteins associated with cell survival such as cyclin D1 and PCNA were also induced more by M-TCM than TCM in all three prostate cancer cell lines." (PMID 32196489, 2020). "Licochalcone A caused G2 and late-G1 arrests in androgen-independent PC-3 prostate cancer cells by affecting the expression of proliferating cell nuclear antigen (PCNA), DNA polymerase δ, Rb and E2F, cyclins B1 and D1, and so on, which led to apoptosis." (PMID 32256642, 2020). "Treatment with kaempferol causes a downregulation of proliferation in human prostate cancer through suppression of proliferating-cell nuclear antigen (PCNA) and vascular cell adhesion molecule-1 (VCAM-1)." (PMID 29736177, 2018). "GHRH antagonists caused a significant decrease in the expression levels of PCNA in prostate cancer cells and the observed tumor growth inhibition was associated with such a decrease on protein levels." (PMID 27448980, 2016). "Proliferating cell nuclear antigen (PCNA) is an essential protein for DNA replication and repair, and high expression of PCNA is considered as a hallmark of cell proliferation, which is associated with high cell proliferation rate in cancers, such as prostate cancer and ovarian cancer." (PMID 27708548, 2016). "The positive correlation between the expression of APE2 and PCNA was most significant in prostate cancer." (PMID 32111912, 2020). "In fact, the inhibition of PCNA phosphorylation on Y211 was shown to inhibit the proliferation of prostate cancer cells." (PMID 32276417, 2020). "A possible mechanism for the oncogenic function of PVT1 exon 9 is by the regulation of PCNA (Proliferating Cell Nuclear Antigen) expression in prostate cancer." (PMID 32117705, 2020). "We found that treatment of PCNA-I1S in combination with DNA damaging agents Cs-137, UV-C, or cisplatin (cisPt) produced additive inhibitory effects on growth of prostate cancer and NSCLC cells." (PMID 31600334, 2019). "Overexpression of PCNA in prostate cancer and non-small cell lung carcinoma (NSCLC) is associated with advanced disease and metastasis, and is a reliable biomarker predicting poor prognosis of cancers of various tissue types." (PMID 31600334, 2019). "Inhibition of PCNA phosphorylation on Y211 using a synthetic peptide was shown to inhibit proliferation of prostate cancer cells and reduce tumor growth in xenograft prostate tumors." (PMID 30126151, 2018). "Our results suggest that targeting PCNA and thereby affecting multiple cellular pathways simultaneously has the potential to improve docetaxel therapy of advanced prostate cancer." (PMID 29545934, 2018). "Expression levels of PCNA correlate positively with other pathological indices in prostate cancer and can serve as an independent prognostic marker." (PMID 25213357, 2015). "The association between EphB6 expression, clinicopathological findings, proliferating-cell nuclear antigen (PCNA; another prognostic marker) and progression of prostate cancer was analyzed." (PMID 25789021, 2015). "Consistent with this line of evidence, we demonstrated that ORC6, DCD6, MCM7 together with PCNA and cyclin E were diminished in quiescent prostate cancer cells." (PMID 26416244, 2015). "Recently, it was reported that phosphorylation of PCNA at tyrosine 211 (Y211) is a promising treatment target in prostate cancer." (PMID 24591761, 2014). "The use of PCNA along with Ki-67 has been suggested as specific proliferative markers of prostate cancer for early cancer diagnosis." (PMID 24403257, 2013). "Coimmunoprecipitation of PCNA with anti-β-2-microglobulin antibody was also confirmed in DU145 prostate cancer cells (lanes D–F)." (PMID 23527218, 2013).
prostate carcinoma (continued). "We recently reported that phosphorylation of PCNA at Y211 is a promising treatment target in prostate cancer." (PMID 22238610, 2012). "Moreover, RNA-binding motif protein 15B (RBM15B) enhances prostate cancer cell proliferation by increasing the stability of proliferating cell nuclear antigen (PCNA) mRNA through YTHDF1-induced m6A methylation." (PMID 40986143, 2025). "Regulation of prostate cancer cell senescence through the FOXM1/PCNA axis." (PMID 40458727, 2025). "Furthermore, R9-AR-PIP and PCNA-I1S reduce cyclin A2 expression in prostate cancer cells expressing both AR-FL and AR-Vs." (PMID 40391771, 2025). "For instance, hydroalcoholic extracts of paddy waste (both husk and straw) exhibited chemopreventive effects in prostate cancer cells, through the modulation of cell cycle regulators, namely Ki-67 proliferative marker and PCNA proliferating cell nuclear antigen." (PMID 40806112, 2025). "In addition, the expression of cyclin D1, PCNA, and p21 is modified leading to proliferation inhibition of distinct prostate cancer cell lines." (PMID 33937075, 2021). "The expression of PCNA is directly and negatively regulated by mesenchymal stem cell-derived exosomes that contain miR-143, which inhibit the proliferation, migration, and invasion of prostate cancer cells and promote apoptosis, thus hindering tumor growth." (PMID 34721621, 2021). "Additionally, specific silencing of PVT1 exon 9 in the MDA PCa 2b prostate cancer cell line using a PVT1 exon 9 specific siRNA resulted in decreased PCNA expression." (PMID 31766781, 2019). "Additionally, the potential association between the expression of EphB6 and proliferating-cell nuclear antigen (PCNA), an independent postoperative prognostic marker for prostate cancer patients, was assessed." (PMID 25789021, 2015). "Furthermore, the expression of PCNA is significantly correlated with Gleason score and vascular invasion in prostate cancer." (PMID 26416244, 2015). "Likewise, PCNA level was found to be higher in prostate cancer than those in high-grade prostatic intraepithelial neoplasia and benign prostatic epithelium." (PMID 26416244, 2015). "Similarly, decreased PCNA contents are observed in melatonin-treated prostate cancer." (PMID 34235199, 2021). "Our recent study shows that targeting PCNA/AR interaction with enzalutamide, PCNA-I1S, R9-AR-PIP, and/or T2AA induces cytotoxicity in both androgen-dependent prostate cancer cells and CRPC cells." (PMID 40391771, 2025). "We found that EXO1 promoted BCL2, CDC25, and PCNA and inhibited BAX expression, and further experiments showed that EXO1 inhibited apoptosis in prostate cancer cells." (PMID 38279172, 2024). "Immunofluorescence showed that shUBE2N-xenograft presented decreased PCNA-positive cells than shNC-xenograft, suggesting that knockdown of UBE2N suppresses prostate cancer tumor growth in vivo." (PMID 38715121, 2024). "For the G2 radiosensitive prostate cancer donors, 60% (3/5) CDKN1A, 40% FDXR, 80% SESN1 and 40% PCNA gene expression exceeded the fold change threshold." (PMID 34638945, 2021). "The same mechanism was shown to be at play in the tumorigenic prostate cancer cell line (MDA PCa 2b), which significantly reduced its PCNA expression when PVT1 exon 9 expression was silenced." (PMID 33796469, 2021). "The expression of PCNA and Ki-67 is increased significantly in patients with BPH or prostate cancer, and the degree of proliferation is related to the clinical grade of prostate cancer." (PMID 27504137, 2016). "Moreover, it inhibited the invasion of prostate cancer cells and lowered the expression of MCM2/MCM3, PCNA, and CDK2." (PMID 37682177, 2023).